EMP1 (epithelial membrane protein 1)
Diseases named in the same sentence as EMP1 in open-access papers (continued):
Sharing a sentence is not in itself a finding about the gene and the disease.
prostate carcinoma (10 papers, 2018 to 2025). A carcinoma that arises from epithelial cells of the prostate gland. "Increased EMP1 expression in patients with prostate cancer occurs at the invasive front and is associated with malignancy." (PMID 31652725, 2019). "Furthermore, EMP1 might be associated with tumor inhibition in other cancers such as nasopharyngeal carcinoma, oral squamous cell carcinoma, and prostate cancer." (PMID 36217151, 2022). "Among different subgroups in prostate cancer scRNAseq data, significant correlations between EMP1/COL3A1 and four EMT genes (VIM, SNAI2, TWIST1, and CTNNB1) were found in the osteoblast subgroup." (PMID 38187400, 2023). "We also identified high levels of expression (4.07-fold upregulation) of EMP1 in our aggressive prostate cancer subtypes which regulates the expression of CD44 to promote stemness." (PMID 37476073, 2023). "For example, EMP1 promotes tumor metastasis by enhancing cell migration in prostate cancer, whereas EMP2 acts as an oncogenic protein in endometrial cancer cells, with high EMP2 related to increased lymphovascular invasion and poor survival." (PMID 33799364, 2021). "EMP1 has been reported to suppress tumor progression across various cancer types, including nasopharyngeal cancer, oral squamous cell carcinoma and prostate cancer." (PMID 33714198, 2021). "We have recently found that EMP1 enhances the progression of prostate cancer in vitro and in vivo, and that the mRNA and protein levels of EMP1 are upregulated in co-cultures of human prostate cancer and stromal cells." (PMID 31652725, 2019). "Overexpression of EMP1 in PC3 prostate cancer cells significantly decreases cell migration and invasiveness." (PMID 31652725, 2019). "We have recently revealed that the expression of a transmembrane protein, epithelial membrane protein 1 (EMP1), is upregulated in co-cultures of human prostate cancer cells and prostate stromal cells." (PMID 31652725, 2019). "The inoculation of prostate cancer cells overexpressing EMP1 into nude mice leads to metastasis to the lymph nodes and lungs, indicating that EMP1 contributes to metastasis." (PMID 31652725, 2019). "EMP1 expression is significantly increased in the prostate cancer samples with higher Gleason scores, compared with those with lower scores." (PMID 31652725, 2019). "In agreement with these previous studies, copine-III was shown to be essential for EMP1-induced prostate cancer cell migration via the activation of the Src–Vav2–Rac1 axis by the loss-of-function and subsequent rescue experiments in our study." (PMID 29867202, 2018). "EMP1-related potentiation of tumor metastasis is supported by the finding that prostate cancer samples with higher Gleason score abundantly express EMP1, compared with those with lower Gleason score." (PMID 29867202, 2018). "We further demonstrated that copine-III plays a role downstream of EMP1 to promote prostate cancer metastasis." (PMID 29867202, 2018). "To determine the relationship between Vav2 and EMP1 in prostate cancer cells, we first confirmed that Vav2 expression levels were similar between LNCaP #2 and #17 cells." (PMID 29867202, 2018). "Using a co-culture assay system with human prostate cancer LNCaP cells and primary human prostate stromal cells, we identified epithelial membrane protein 1 (EMP1) as a gene with elevated expression in the cancer cells." (PMID 29867202, 2018). "CPNE3 could promote cell motility by interacting with epithelial membrane protein 1 in prostate cancer cells." (PMID 37469397, 2023). "Furthermore, the existence of these EMP1+/COL3A1+ fibroblasts was also verified in prostate cancer and renal cancer BoM samples, suggesting the importance of these fibroblasts from a pan-cancer perspective." (PMID 38187400, 2023). "In prostate cancer, more EMP1+/COL3A1+ osteoblasts were found instead of fibroblasts." (PMID 38187400, 2023).
prostate carcinoma (continued). "Furthermore, there was a significant correlation between COL3A1 and EMP1 in osteoblasts, suggesting the enrichment of COL3A1+/EMP1+ cells during the BoM process in prostate cancer." (PMID 38187400, 2023). "In contrast, others uncovered the potential role of EMP1 as a suppressor of prostate cancer." (PMID 31652725, 2019). "Thus, future studies are required to explain the discrepancy of EMP1 functions in breast and prostate cancers." (PMID 31652725, 2019). "The functions of EMP1 in breast and prostate cancers are reported to be controversial." (PMID 31652725, 2019). "Considering not a large sample size of the experiment, the continuous attempt to increase the human prostate cancer samples for analyzing them would be necessary to strengthen the clinical significance of EMP1 expression in metastasis and poor prognosis of the prostate cancer." (PMID 29867202, 2018). "Because Src is reported to be activated downstream of copine-III, we examined whether the EMP1–copine-III axis could contribute to the increase in Src activity in prostate cancer cells." (PMID 29867202, 2018). "Prospective clinical studies in the future may provide a certain evidence that EMP1 expression is related to prognosis of prostate cancer." (PMID 29867202, 2018). "Moreover, EMP1 was highly expressed in prostate cancer samples obtained from patients with higher Gleason score." (PMID 29867202, 2018). "Finally, we analyzed the expression of EMP1 in human prostate cancer samples." (PMID 29867202, 2018). "In prostate cancer, EMP1 is highly expressed in patients with a higher Gleason score, and increasing EMP1 levels significantly increases cancer cell migration, resulting in tumor metastasis, implying that EMP1 may play an important role as a positive regulator of tumor metastasis." (PMID 37008256, 2023). "Cell lines overexpressing EMP1 presented mitochondrial-dependent apoptosis and VEGF-C-mediated tumor angiogenesis inhibition in a colorectal and prostate cancer study." (PMID 36217151, 2022). "Then, to explore the characteristics of EMP1 in prostate cancer cells, we generated LNCaP cells stably expressing FLAG-tagged EMP1, and observed the localization of FLAG-EMP1 at the plasma membrane." (PMID 29867202, 2018). "The sizes of the primary tumor in the prostate glands of the engrafted mice are identical between control and EMP1-overexpressed LNCaP cells, suggesting that EMP1 does not affect the proliferation of prostate cancer cells." (PMID 31652725, 2019).
bladder cancer (9 papers, 2020 to 2025). "Epithelial membrane protein 1 (EMP1) deficiency promotes bladder cancer cell migration and confers resistance to ferroptosis/oxidative stress, thereby promoting bladder cancer metastasis via PPARG." (PMID 36077637, 2022). "In this particular subtype, the prognosis of bladder cancer can be independently evaluated by a risk model composed of EMP1, FGFR1, and CAVIN1 genes." (PMID 32695477, 2020). "On the other hand, EMP1 exhibited a wide distribution in bladder cancers but showed a particular concentration in endothelial cells." (PMID 38341586, 2024). "High levels of EMP1 expression in bladder cancer contribute to lower overall survival rates and are strongly correlated with immune cell infiltration." (PMID 38341586, 2024). "On the other hand, EMP1 knockdown promoted metastasis by resisting oxidative stress and ferroptosis in bladder cancer cells." (PMID 37386026, 2023). "In cisplatin-resistant bladder cancer cell lines, FLRT2, HOXC5, SCD, GRM7, HMGA1, ETV7, and SCO2 were highly expressed, while EMP1, SERPINA6, and ZNF124 exhibited lower expression levels." (PMID 39744172, 2025). "Among the six identified survival-related genes, three-genes, EMP1, FGFR1, and CAVIN1, were identified as potential independent prognostic markers for the specific bladder cancer subtype with clinical features described." (PMID 32695477, 2020). "The absence of EMP1 stimulates bladder cancer cell migration by activating the PPARγ signaling pathway." (PMID 40612666, 2024).
glioblastoma (9 papers, 2018 to 2025). The most malignant astrocytic tumor (WHO grade IV). "EMP1 is upregulated in glioblastoma multiforme and its inhibition decreases proliferation and invasiveness of tumor." (PMID 33747919, 2021). "Silencing EMP1 expression in glioblastoma cells inhibits their proliferation and invasiveness, as well as the expression of CD44 and matrix metalloprotease (MMP)-2." (PMID 31652725, 2019). "Moreover, in glioblastoma, EMP1 levels can be regulated by the epidermal growth factor receptor ligand, thereby contributing to the oncogenic role of the epidermal growth factor receptor in glioblastoma." (PMID 41285728, 2025). "EMP1 contributes to the metastasis of glioblastoma multiforme (GBM)." (PMID 31652725, 2019). "In glioblastoma, EMP1 has also been found to be a suppressor gene for killing function of T cells, which can be used to improve the effector function of T cells, increase the infiltration of T cells into the tumor site, and reduce the tumor growth by knocking down the EMP1 gene in CD8 T cells." (PMID 41285728, 2025). "Indeed, methylation of EMP1 and EMP2 in human cancer is rarely reported, although methylation of EMP3 was previously detected in NSCLC and glioblastoma, suggesting different gene regulatory programs in EMPs." (PMID 33799364, 2021). "Besides EMP1, EMP2 has been shown to be upregulated in more than 70% of both serous and endometrioid ovarian cancers, and to enhance tumor growth of glioblastoma by promoting angiogenesis, partially by increasing vascular endothelial growth factor-A expression in glioblastoma cells." (PMID 29867202, 2018).
nasopharyngeal carcinoma (9 papers, 2019 to 2023). A carcinoma arising from the nasopharyngeal epithelium. "The decrease of EMP1 expression is significantly correlated with the T stage, lymph node metastasis, clinical stage, and histological grading of nasopharyngeal carcinoma (p < 0.05)." (PMID 36217151, 2022). "In contrast, in carcinoma of the nasopharynx, stomach, breast, urothelium, and prostate, EMP1 reduces cell migration and invasion and increases apoptosis and caspase-9 expression." (PMID 33747919, 2021). "Overexpression of EMP1 in nasopharyngeal carcinoma cells decreases cell viability, migration and invasion, and induces apoptosis." (PMID 31652725, 2019). "Furthermore, EMP1 was disclosed as having a function to prevent nasopharyngeal cancer proliferation and metastasis by enhancing apoptosis and reducing angiogenesis." (PMID 33714198, 2021). "For example, Epithelial Membrane Protein 1 (EMP1) is expressed in high levels in human cancers and was shown in vitro to reduce cell migration and invasion, and was also shown to increase apoptosis and caspase-9 expression in carcinoma of the nasopharynx, stomach, breast and prostate." (PMID 35054064, 2022).
lung carcinoma (8 papers, 2015 to 2025). "In lung cancer, EMP1 has been implicated as a biomarker for gefitinib resistance." (PMID 36936167, 2023). "For instance, EMP1 has been recognized as a biomarker for gefitinib resistance in lung cancer and contributes to prednisolone resistance in patients with acute lymphoblastic leukemia." (PMID 38728370, 2024). "EMP1 overexpression in lung cancer enhances proliferation through PI3K/AKT activation." (PMID 41458590, 2025). "EMP1 is also a biomarker of gefitinib resistance, and it has been linked to a lack of complete or partial response to gefitinib in lung cancer patient samples, as well as clinical progression to secondary gefitinib resistance." (PMID 37008256, 2023). "EMP1 is correlated with clinical resistance to gefitinib in lung cancer." (PMID 37547756, 2023). "EMP1 contributed to gefitinib resistance in lung cancer as well as in head and neck cancer, indicating that EMP1 could be a marker of therapeutic efficacy." (PMID 37386026, 2023). "Furthermore, EMP1, expression of which was higher in the glucose-cultured ITGA6 positive cells, is a biomarker of resistance to another TKI, gefitinib, in lung cancer." (PMID 29796188, 2018). "In addition, EMP-1, one of EMP family members, has also been reported to be involved in activation of PI3K/Akt pathway in lung cancer." (PMID 26472188, 2015).
acute lymphoblastic leukemia (6 papers, 2019 to 2024). Leukemia with an acute onset, characterized by the presence of lymphoblasts in the bone marrow and the peripheral blood. "In acute lymphoblastic leukemia, EMP1 is a novel poor prognostic factor in pediatric leukemia that regulates prednisolone resistance, cell proliferation, migration, and adhesion." (PMID 37008256, 2023). "The significance of EMP1 expression has been reported in acute lymphoblastic leukemia (ALL)." (PMID 31652725, 2019).
cervical carcinoma (6 papers, 2021 to 2025). A carcinoma arising from either the exocervical squamous epithelium or the endocervical glandular epithelium. "MIR31HG promoted the invasiveness of cervical carcinoma cells by sponging miR-361-3p and positively modulate its target, epithelial membrane protein 1 (EMP1)." (PMID 37950038, 2024). "MIR31HG serves as an oncogene in cervical carcinoma by acting as a sponge for miR-361-3p to modulate the miRNA target EMP1." (PMID 37636269, 2023). "The competitive binding of long noncoding RNAMIR31HG to miR-361-3p can regulate EMP1 expression, affecting the progression of cervical cancer." (PMID 36217151, 2022). "The expression of the EMP1 gene is also significantly downregulated in cervical cancer biopsy tissues." (PMID 36217151, 2022). "This is an interesting study revealing that the MIR31HG-miR-361-3p-EMP1 axis plays a vital role in cervical carcinoma progression, and it also indicates a novel axis of MIR31HG-miR-361-3p in tumor development." (PMID 34485123, 2021). "Overexpression of EMP1 could induce apoptosis and inhibit cell migration and invasion, while restoring EMP1 expression rescued cell growth, clonogenic potential, and invasive trait of cervical carcinoma cell." (PMID 35432717, 2022). "In cervical cancer, Li (2020) verified that MIR31HG silencing inhibited cervical cancer cell proliferation and invasion, whereas anti-miR-361-3p or overexpression of epithelial membrane protein 1 (EMP1) led to the opposite effect." (PMID 37636269, 2023).
malaria (6 papers, 2017 to 2023). Malaria is a serious and sometimes fatal disease caused by a parasite that commonly infects a certain type of mosquito which feeds on humans. "Placental pathology in malaria is caused by expression of unique Pf EMP1 protein on iRBC which helps the parasite to sequester into the placenta." (PMID 28791290, 2017). "Plasmodium falciparum Erythrocyte Membrane Protein 1 (Pf EMP1) has been proposed as the major variant surface antigen (VSA) of the most virulent malaria parasite known as P. falciparum." (PMID 28924231, 2017). "We investigated the diversity and population structure of var gene sequences encoding the Pf EMP1 DBLα domain of P. falciparum causing uncomplicated malaria." (PMID 28924231, 2017). "The binding motifs for the miR-92a-3p in Pf3D7_EMP1 transcripts were identified to reside within the sequences those code for DBLα domains, disordered regions as well as CIDRγ domains, possibly enabling disruption of variants associated with clinical malaria." (PMID 36941394, 2023). "Presentation of the variant antigen Plasmodium falciparum erythrocyte membrane protein 1 (EMP1) at the surface of infected red blood cells (RBCs) underpins the malaria parasite’s pathogenicity." (PMID 37575395, 2023). "Women, who have malaria during pregnancy, develop Pf EMP1-specific antibodies and these antibodies protect women from malaria in subsequent pregnancies." (PMID 28791290, 2017). "Many studies have shown that individuals with uncomplicated malaria exhibit a broad range of antibody responses and harbor parasites that express diverse Pf EMP1 variants." (PMID 28924231, 2017). "One peculiarity of human malaria parasites is that these species contain several genes whose proteins are involved in trafficking and the display of membrane proteins on the surface of infected erythrocytes, including three EMP1-trafficking protein-coding genes and SURFIN4.2." (PMID 29716542, 2018).
esophageal cancer (4 papers, 2019 to 2022). A primary or metastatic malignant neoplasm involving the esophagus. "In contrast, EMP-1 transcript levels are the lowest in oral cancer, laryngeal, gastric, and esophageal cancers." (PMID 36217151, 2022). "A previous study on esophageal carcinoma reported overexpression of EMP1 inhibits cell proliferation by cell cycle arrest at S phase, whereas in a leukemic cell line, EMP1 inhibition has been shown to induce cell cycle arrest at G1 phase." (PMID 33747919, 2021). "EMP1 mRNA levels are low in 15 pairs of the esophageal cancer lesions compared with the adjacent normal areas, and overexpression of EMP1 in esophageal carcinoma cells inhibits their proliferation." (PMID 31652725, 2019). "In addition, multiple studies have shown that the levels of EMP1 protein are downregulated in esophageal cancer cells, the growth of esophageal cancer cells stably expressing EMP1 is slow, and genes related to cell signal transduction and cell adhesion are down-regulated." (PMID 36217151, 2022).
laryngeal carcinoma (4 papers, 2021 to 2025). Carcinoma that arises from the laryngeal epithelium. "It has been reported that EMP1 expression is significantly lower in laryngeal carcinoma compared to normal adjacent tissues." (PMID 33714198, 2021). "For example, it has been regularly reported that laryngeal cancer tissues differentially express certain genes, including EMP1, HOXB9, DPY19L2P1, MMP1, and KLHDC7B, representing independent prognosis predictor genes of laryngeal cancer." (PMID 39452555, 2024).
lobular carcinomas (4 papers, 2007 to 2025). "EMP1 expression level can be used to to differentiate between invasive ductal and lobular breast carcinoma." (PMID 37547756, 2023). "Immunohistochemistry confirmed higher expression of DVL1 and EMP1 in lobular carcinomas and of DDR1 in ductal carcinomas (p < 0.0001)." (PMID 17389037, 2007). "EMP1 may represent a novel immunohistochemical marker helpful in distinguishing between invasive ductal and lobular carcinomas." (PMID 23497265, 2013). "Because lobular carcinoma resists neoadjuvant therapy, the survival rate of patients with these tumors is lower than that of ductal carcinoma patients, and these data may suggest that EMP1 has the function of promoting tumor progression." (PMID 41458590, 2025). "Epithelial membrane protein 1 (EMP1) was the only upregulated gene involved in cell growth and proliferation in lobular carcinomas." (PMID 17389037, 2007).
lymph node metastasis (4 papers, 2022 to 2025). "The results showed that the expression level of EMP1 in TNBC was lower than that in normal tissues, and its expression level was related to T stage, lymph node metastasis, clinical stage and overall survival." (PMID 41458590, 2025).
non-small cell lung carcinoma (4 papers, 2020 to 2021). A group of at least three distinct histological types of lung cancer, including non-small cell squamous cell carcinoma, adenocarcinoma, and large cell carcinoma. "EMP1 expression in non-small cell lung carcinoma is associated with clinical resistance to gefitinib." (PMID 33747919, 2021). "In this study, we analyzed the expression of EMP1-3 and investigated the biological function of EMP2 in non-small cell lung cancer (NSCLC)." (PMID 33799364, 2021). "EMP3 and EMP1 have been reported to be involved in the PI3K/Akt pathway in HCC, and in the tumorigenesis of non-small cell lung cancer." (PMID 32857809, 2020).
oral squamous cell carcinoma (4 papers, 2020 to 2025). "In oral squamous cell carcinoma, however, high expression of EMP1 was related to an increased capability to metastasize to nodes." (PMID 33799364, 2021).